SPMIP2 (sperm microtubule inner protein 2)
Synonyms: C4orf45; FLJ25371
Tractability: No criterion of Open Targets' tractability assessment is met for any kind of drug.
Gene: Protein-coding gene on chromosome 4 (158,893,134 to 159,038,760, reverse strand). Ensembl gene ENSG00000164123.
Subcellular location (Human Protein Atlas): Mid piece; Principal piece
Gene Ontology:
Molecular function: protein binding
Genetic constraint (gnomAD): Loss-of-function variants: 20 observed, 15.66 expected, observed/expected ratio (o/e) 1.28, 90% interval 0.89 to 1.79. The upper end of that interval is the gene's LOEUF score, 1.79, which puts it in group 6 of 6, group 1 being the genes least tolerant of losing a copy. Missense variants: 156 observed, 156.88 expected, observed/expected ratio (o/e) 0.99, 90% interval 0.87 to 1.14. Synonymous variants: 49 observed, 56.2 expected, observed/expected ratio (o/e) 0.87, 90% interval 0.69 to 1.11.
Homologues: Orthologues: chimpanzee SPMIP2 (97% identical), macaque SPMIP2 (92% identical), dog SPMIP2 (72% identical), pig SPMIP2 (70% identical), guinea pig SPMIP2 (58% identical), mouse Spmip2 (50% identical), rat Spmip2 (49% identical), tropical clawed frog spmip2 (34% identical).